IL12RB2 (interleukin 12 receptor subunit beta 2)
Diseases named in the same sentence as IL12RB2 in open-access papers (continued):
Sharing a sentence is not in itself a finding about the gene and the disease.
tuberculosis (4 papers, 2012 to 2025). A chronic, recurrent infection caused by the bacterium Mycobacterium tuberculosis. "This is the first report of the analysis of the polymorphism −237C to T in the IL-12Rβ2 gene and its association with tuberculosis." (PMID 22509293, 2012). "The one of the objectives of the present study was to detect the presence of the −237 C/T polymorphism (SNP ID: rs11810249) in the IL-12Rβ2 promoter region and to assess its distribution among tuberculosis patients, household contacts and miscellaneous healthy volunteers." (PMID 22509293, 2012). "The 8 low expressers of IL-12Rβ2 mRNA (Low-C) had the highest transcript levels of IL-4 compared to the Low-T, (p = 0.01) & High-C (p = 0.02) group of tuberculosis patients and healthy volunteers examined, (p = 0.002)." (PMID 22509293, 2012). "The mRNA expression of the 28 tuberculosis patients, investigated showed a mixed expression profile of the IL-12Rβ2 mRNA expression." (PMID 22509293, 2012). "As IL-12Rβ2 surface expression was low in unstimulated circulating PBMCs (Data not shown), experiments were carried out to determine mRNA expression of the IL-12Rβ2 subunit at the baseline level in peripheral blood leucocytes derived from 28 tuberculosis patients." (PMID 22509293, 2012). "Hence elevated levels of IFN-α could be a pre-disposing factor for the onset of clinical tuberculosis despite its potency to induce expression of IL-12Rβ2 mRNA." (PMID 22509293, 2012).
COVID-19 (3 papers, 2021 to 2025). A disease caused by infection with severe acute respiratory syndrome coronavirus 2. "However, IL12RB1 and IL12RB2 transcript levels as well as those encoding for the cytokines, IL15 and IL12 (IL15 and IL12A, respectively) decreased in life-threatening COVID-19 and MIS-C." (PMID 41285788, 2025).
Crohn disease (3 papers, 2012 to 2024). A gastrointestinal disorder characterized by chronic inflammation involving all layers of the intestinal wall, noncaseating granulomas affecting the intestinal wall and regional lymph nodes, and transmural fibrosis. "Previous work has identified elevated IL-12, specifically IL-12RB2, in the mucosa of patients with active Crohn’s disease." (PMID 30998704, 2019).
periodontitis (3 papers, 2021 to 2025). An acute or chronic inflammatory process that affects the tissues that surround and support the teeth. "In the Periodontitis group, the most significant genes included CTTNBP2NL, SOS1, RNF213, and IL12RB2." (PMID 40458179, 2025).
systemic lupus erythematosus (3 papers, 2019 to 2021). An autoimmune multi-organ disease typically associated with vasculopathy and autoantibody production. "In this study, we set out to investigate the serum IL-35 levels and the surface levels of IL-12Rβ2 and gp130 in CD3+CD4+, CD3+CD4─ and CD3─CD4─ lymphocyte subpopulations in systemic lupus erythematosus (SLE) patients (n=50) versus healthy controls (n=50)." (PMID 34149710, 2021). "Surprisingly, in the current study, we also show that the WAS chimera model is not impacted by global Il12rb2 deficiency and our previous work has shown that B cell-intrinsic IFNAR is also dispensable for lupus development in this model." (PMID 30740104, 2019).
atherosclerosis (2 papers, 2023 to 2025). A disease characterized by the build-up of fatty material and calcium deposition in the arterial wall resulting in partial or complete occlusion of the arterial lumen. "IL12RB2, involved in IL-35 control, plays a crucial role in atherosclerosis and inflammation regulation." (PMID 40459864, 2025). "IL12RB2 is involved in IL-35 control, which is important for atherosclerosis and inflammation and has been shown to inhibit ischemia/hypoxia-induced angiogenesis, suggesting that this anti-inflammatory cytokine plays new roles at the recovery stage of angiogenesis." (PMID 37240062, 2023).
celiac disease (2 papers, 2009 to 2012). An autoimmune genetic disorder with an unknown pattern of inheritance that primarily affects the digestive tract. "It remains to be elucidated whether IL23R, IL12RB2 or another gene at 1p31 confers risk to celiac disease." (PMID 19175939, 2009). "Hence, the IL12A association and the proximity of IL12RB2 to IL23R (which appears linked to celiac disease), suggest that the genes of the IL12 pathway are particularly interesting to investigate in future genetic studies of celiac disease." (PMID 19175939, 2009). "Variants in the LD block upstream of IL23R or in the downstream LD block covering IL12RB2, may explain the linkage to celiac disease in the Finnish population." (PMID 19175939, 2009).
head and neck cancer (2 papers, 2018 to 2020). A primary or metastatic malignant neoplasm affecting the head and neck. "Previous studies have found associations of IL12RB1 and IL12RB2 gene-SNPs with cervical, vulvar and head and neck cancers." (PMID 32973967, 2020). "IHC examination for head and neck cancers showed that high levels of IL12Rβ2 correlated with a higher probability of subsequent development of metastasis." (PMID 30218063, 2018).
hyperlipidemia (2 papers, 2020 to 2021). "In addition, we observed an increased IL-12Rβ2, which account for mediating the immunosuppressive functions, in splenic Tregs and aortic Tregs in hyperlipidemia status; this suggests that IL-35 signaling is induced in splenic ApoE–/– Tregs and atherosclerotic aortas." (PMID 34622804, 2021).
inflammatory bowel disease (2 papers, 2009 to 2020). A spectrum of small and large bowel inflammatory diseases of unknown etiology. "Association of genetic markers in the interleukin-23 receptor (IL23R) gene, and the intergenic region between IL23R and IL12RB2, with inflammatory bowel disease (IBD) was first identified in 2006." (PMID 19175939, 2009).
lymphoproliferative disorder (2 papers, 2014 to 2025). "IL-12Rβ2-deficient mice older than age 1 year were previously reported to experience spontaneous systemic development of an autoimmune and lymphoproliferative disorder associated with enhanced susceptibility to tumor formation." (PMID 24760014, 2014). "Notably, Il12rb2 knockout mice develop an autoimmune and lymphoproliferative disorder characterized by oligoclonal B cell proliferation and up-regulation of systemic IL-636, suggesting that increased IL12 signaling mediates anti-BCL immunity." (PMID 40760075, 2025).
multiple sclerosis (2 papers, 2011 to 2025). A progressive autoimmune disorder affecting the central nervous system resulting in demyelination. "It is also relevant that improvement in some patients with multiple sclerosis treated with IFN-β is thought to be underpinned by upregulation of the signalling receptor subunit for IL-12p70, i.e., IL-12Rβ2." (PMID 40868162, 2025).
sarcoidosis (2 papers, 2012 to 2014). Sarcoidosis is a multisystemic disorder of unknown cause characterized by the formation of immune granulomas in involved organs. "IL-12Rβ1 and IL-12Rβ2 levels are elevated in sarcoidosis patients." (PMID 25386143, 2014).
uveitis (2 papers, 2013 to 2014). An inflammatory process affecting a part of or the entire uvea. "Given the fact that these related genes (IL-12B, IL-12Rβ1 and IL-12Rβ2) play an important role in Th1 and Th17 related immune responses, we wanted to verify the potential evidence of an association of polymorphisms in these genes with uveitis." (PMID 24859272, 2014).
abscesses (1 paper, 2024). "Notably, Il12rb2+/+ mice showed increased mucosal inflammation and tunica muscularis thickening, as well as increased mononuclear cell infiltration throughout the entire cLP and the formation of crypt abscesses, submucosal edema, goblet cell depletion, and crypt distortion." (PMID 38498592, 2024).
aging (1 paper, 2019). A developmental process that is a deterioration and loss of function over time. "The functional relevance of IL12RB2 rs3790558 on cognitive aging remains to be elucidated." (PMID 31649612, 2019). "On another note, our results also indicated the epistatic effects between the IL12RB2 and IL12A genes in modulating cognitive aging by employing the GMDR method." (PMID 31649612, 2019).
Allergy (1 paper, 2018). An allergy is an immune response or reaction to substances that are usually not harmful. "The biological relevance of the IEC-associated IL-12Rβ2 was assessed in vivo in a mouse model of food allergy characterized by allergy-associated diminished intestinal levels of IL-12 and in chimeric mice that lack the IL-12Rβ2 chain on IECs." (PMID 29896198, 2018).
cerebral malaria (1 paper, 2022). A sequestration of Plasmodium falciparum in the brain, which can cause coma and/or seizures. "T‐bet and IL‐12Rβ2, a marker of Th1 commitment are required for experimental cerebral malaria." (PMID 36131528, 2022).
cervical cancer (1 paper, 2023). A primary or metastatic malignant neoplasm involving the cervix. "With regard to IL12RB2 rs2229546, our results are in line with another study that found an association between rs2229546 and a reduced risk of cervical squamous cell carcinoma and HPV-18-positive cervical cancer." (PMID 37108754, 2023).
E. coli infection (1 paper, 2024). "In this study, E. coli infection up-regulated key genes in the Th17 cell differentiation pathway, including FOS, VEGFA, IL12RB2, IFN-ALPHA-8, and IFN-ALPHA-13, indicating widespread activation of the immune system." (PMID 39707535, 2024).
food allergy (1 paper, 2018). Gastrointestinal disturbances, skin eruptions, or shock due to allergic reactions to allergens in food. "Subsequently we investigated the role of IEC-associated IL-12Rβ2 in the regulation of immune response using a well-established mouse model of food allergy." (PMID 29896198, 2018).
glioblastoma multiforme (1 paper, 2018). "We conducted expression profiling of CD274 (PD-L1), GATA3, IFNG, IL12R, IL12RB2, IL4, PDCD1 (PD-1), PDCD1LG2 (PD-L2), and TBX21 (T-bet) using data of 158 glioblastoma multiforme (GBM) patients with clinical information available at The Cancer Genome Atlas." (PMID 29721184, 2018).
glioma (1 paper, 2025). A benign or malignant brain and spinal cord tumor that arises from glial cells (astrocytes, oligodendrocytes, ependymal cells). "We confirmed that the expression profiles of relevant IL-12R genes (Il12rb1, Il12rb2, and Stat4) are comparable between human gliomas and the murine GB cell lines (CT-2A, GL261, and 005), supporting the utility of these mouse models for studying IL-12-mediated mechanisms in GB." (PMID 40842154, 2025).
HCMV infection (1 paper, 2015). "Although further studies are required to define the “within subset” effects of HCMV infection, our data suggest that reduced expression of IL-18Rα or reduced ability to upregulate IL-12Rβ2 among NK cells from HCMV-infected individuals may partially explain their failure to produce IFN-γ." (PMID 25855356, 2015).
Immunodeficiency (1 paper, 2022). Failure of the immune system to protect the body adequately from infection, due to the absence or insufficiency of some component process or substance. "With this consideration, we have noted the presence of rare variants in other immunodeficiency genes (JAK2, JAK3, IL17RA, IL12RB2, CARD14, and TYK2) in our various patients, which could feasibly contribute to the penetrance and/or differences in the clinical phenotypes of the patients." (PMID 36672844, 2022).
influenza infection (1 paper, 2022). "Upon influenza infection of the recipients, GFP+ ILC2s were found to have downregulated GATA3 expression and upregulated IL-12Rβ2 and IL-18Rα, becoming so-called ex-ILC2s that produced IFNγ upon ex vivo stimulation with IL-12 and IL-18." (PMID 36052086, 2022).
liver cirrhosis (1 paper, 2017). "Moreover, we have provided evidence that IL12RB2 polymorphisms are associated with liver cirrhosis and an increased concentration of disease-specific AMA in sera of PBC patients." (PMID 28299343, 2017).
mucositis (1 paper, 2024). Mucositis is inflammation and damage of the mucous membranes lining the mouth and other parts of the gastrointestinal (GI) tract. "The potentially useful role of interleukin 12 receptor beta 2/tumor necrosis factor receptor superfamily member 8 (IL12RB2/TNFRSF8) ratio as a biomarker in the differential diagnosis between OLP and other chronic nonspecific mucositis has emerged." (PMID 38672786, 2024).
ovarian tumors (1 paper, 2023). "For example, we observed that IL12A and IL12RB2 being upregulated in ovarian tumors of current low‐dose aspirin users compared with never users, which are inflammatory genes included in the cytokine‐cytokine receptor interaction pathway but are also known to enhance Th1 immune response." (PMID 37525619, 2023).
prostate carcinoma (1 paper, 2023). A carcinoma that arises from epithelial cells of the prostate gland. "Furthermore, a generalized linear mixed model identified statistically significant associations between prostate cancer risk and SNPs in IL12RB2, IL13, IL17A, IL4R, MAPT, and TFNRS1B." (PMID 37108754, 2023).
rheumatoid arthritis (1 paper, 2012). A chronic, systemic autoimmune disorder characterized by inflammation in the synovial membranes and articular surfaces. "IL-17 has been reported not only to drive the T-helper type 17 immune pathway, but also to regulate the T-helper type 1 pathway by decreasing IL-12 and IL-12RB2 subunit expression, especially in patients with rheumatoid arthritis." (PMID 22405131, 2012).
rosacea (1 paper, 2021). A chronic erythematous skin disorder that affects the face. "We also identified the up-regulated transcription factors enriched in the IL12 signaling pathway, and up-regulated expression of IL12RB2 in rosacea lesions." (PMID 34290700, 2021).
schistosomiasis (1 paper, 2014). An infectious disease caused by parasitic trematodes of the genus Schistosoma that colonize human blood vessels and release eggs that can cause granulomatous reactions leading to acute (swimmer's itch or acute schistosomiasis syndrome) or chronic disease. "In IL-12Rβ2-deficient mice both IFN-γ and TNF-αwere absent, pointing to an IL-12/IFN-γ axis in protection in mice with schistosomiasis." (PMID 25398130, 2014).
Sepsis (1 paper, 2025). Sepsis is defined as life-threatening organ dysfunction caused by a dysregulated host response to infection. "Using a sepsis mouse model, they demonstrated that IL-35 suppresses VCAM-1 expression via the IL-12Rβ2:gp130 heterodimeric receptor and inhibits the MAPK-AP-1 signaling pathway." (PMID 39974277, 2025).
small cell lung carcinoma (1 paper, 2025). Small cell lung cancer (SCLC) is a highly aggressive malignant neoplasm, accounting for 10-15% of lung cancer cases, characterized byrapid growth, and early metastasis. "For small cell lung cancer, ACADSB, CEACAM6, COX6B1, CPXM2 and IL12RB2 continued to show significant associations." (PMID 41340014, 2025). "Our study identified five candidate proteins for small cell lung cancer: ACADSB, CEACAM6, COX6B1, CPXM2 and IL12RB2." (PMID 41340014, 2025).
T cell lymphoma (1 paper, 2012). "The highest activity observed in Jurkat cells (human T cell lymphoma) may be due to the fact that expression of IL-12Rβ2 is primarily associated with Th1 type of T cells." (PMID 22509293, 2012).
viral infections (1 paper, 2024). "In addition, Il12rb2, F2, and Masp2 are involved in the activities of the cellular immune system and play important roles in viral infections and cancer." (PMID 38225547, 2024).
ZIKV infection (1 paper, 2021). "In addition, the presence of rare variants in IL12RB2 gene sheds light on possible contributions of early immune-response to ZIKV infection." (PMID 34125832, 2021).
tumor (36 papers, 2009 to 2025). "This group observed that stromal FoxP3/CD3 ratio, tumor IL-12Rβ2, and tumor IL-7R were associated with recurrence." (PMID 34880292, 2021). "We have previously shown that the IL-12RB2 gene, encoding the IL-12R chain essential for IL-12 signal transduction, functions as a tumor suppressor in human neoplastic B cells from various chronic lymphoproliferative disorders and acute lymphoblastic leukemia." (PMID 19582164, 2009). "In our samples, we observed a high percentage of tumor cells harboring IL12RB2 mutations (i.e., high CCF), though it remains unclear whether the IL12RB2 mutations play any functional roles in influencing the inflammatory pathways." (PMID 34075047, 2021). "To validate whether expression of the three candidate genes (TNFSF4, TNFRSF18, and IL12RB2) in the tumor microenvironment is implicated in NK cell migration toward cancer cells, we conducted a Transwell migration assay using GBM U87MG cells, T cells, and NK cells derived from PBMCs." (PMID 36694264, 2023). "SNPs in the IL12RB2 gene associated with BC reduction may enhance IL-12 signaling pathway in cytotoxic T cells and promote Th1 cell differentiation, both of which promote anti-tumor actions at tumor sites." (PMID 32973967, 2020). "Subclone 11 contained EIF4G3, IL12RB2, and PDE4B mutations, and all three mutations had zero allele frequencies in the tumor sample P6_T11, indicating the possibility of secondary driver genes for this subclone." (PMID 34075047, 2021). "Literature data supported the involvement of IL-12Rβ2 in tumour cell proliferation, apoptosis, and metastasis." (PMID 33959797, 2021). "The downregulation of IL-12Rβ2 in lung AC seems to be a tumour escape mechanism, and the IL-12Rβ2 expression has been negatively associated with tumour progression." (PMID 33959797, 2021). "In the immune microenvironment, the tumor expression level of IL-12Rβ2 was proven to be an independent predictor of recurrence in patients with stage I LUAD26." (PMID 31004093, 2019). "In the primary tumor, TNFα induces EMT and expression of IL12Rβ2 to promote tumor invasion and migration." (PMID 30218063, 2018). "IL12RB2 behaves as a tumor suppressor in human chronic B-cell malignancies, and its silencing is an early event in B-cell malignant transformation." (PMID 25475780, 2015). "In this connection, we investigated the functionality of IL-12R on in vitro expanded NBEC since immunohistochemical studies disclosed IL-12Rβ2 expression in NBEC surrounding the tumor." (PMID 19582164, 2009). "We measured Il12rb2 transcript levels in tumor-bearing mice that received rIL-12 treatment." (PMID 40842154, 2025). "IL12RB2 is essential for IL-12 signal transduction and functions as a tumor suppressor." (PMID 36694264, 2023). "In conclusion, we identified TNFRSF18, TNFSF4, and IL12RB2 as biomarkers that predict response to NK cell therapeutics by studying the tumor immune microenvironment using NanoString and qRT-PCR analyses in patients with recurrent GBM who received activated NK cell treatment." (PMID 36694264, 2023). "Notably, neo-antigens increased with increasing expression of IFNγ and IL12RB2, indicating a Th1 skewed signature, as is desirable in an anti-tumor response." (PMID 29487705, 2018). "Some studies have shown that the IL-12Rβ2 chain or IL-23R exhibited tumor suppressor functions." (PMID 30662466, 2018). "IL-12Rβ2 can function as a tumor suppressor gene and can induce apoptosis in cancer cells." (PMID 24351840, 2013). "Interestingly, transient increase in the levels of Il12b and Il12rb2 in splenocytes from mice treated with calcitriol and its analogs can contribute to the lack of effect on the Foxp3 expression level during the later stage of tumor progression." (PMID 30037009, 2018). "ISM1 was selected as a negative prognosis factor in a previously published 21-gene signature related to the UM tumor microenvironment, while MTUS1 and IL12RB2 were considered as indicators of favorable prognosis." (PMID 38339073, 2024).